APOE (apolipoprotein E)
Diseases named in the same sentence as APOE in open-access papers (continued):
Sharing a sentence is not in itself a finding about the gene and the disease.
liver cancer (5 papers, 2009 to 2025). An epithelial or non-epithelial malignant neoplasm that arises from the liver. "Besides, the polymorphism of APOE has been investigated in liver cancer." (PMID 36506554, 2022). "Antigenicity, molecular weight, subcellular localization and expression site predictions were used to shortlist liver cancer associated proteins including AMBP, CFB, CDHR5, VTN, APOBR, AFP, SERPINA1 and APOE." (PMID 39752339, 2025). "HA1 transgenic mice under the control of the liver specific apoE promoter presented with hepatic dysplasia and ultimately liver cancer; thus, the role of cytidine deamination remains open." (PMID 19843348, 2009). "The E4 allele of APOE can function as a protective factor in reducing inflammation and liver fibrosis in HCV-infected patients, which may decrease the risk of liver cancer." (PMID 36506554, 2022). "Fu and colleagues constructed a LCSOV (liver-cancer-specific oncolytic virus) in which the essential viral glycoprotein H gene (gH gene) was controlled by both an apoE-AAT liver-specific promoter and the presence of complementary sequences to miR-122, miR-124a and let-7a in its 3’ UTR." (PMID 24069256, 2013). "Similarly, it is identified that ApoE exerts a tumor-suppressive effect in liver cancer." (PMID 36506554, 2022).
multiple myeloma (5 papers, 2022 to 2025). "Given that ApoE is a protein usually co-deposited in light chain amyloidosis, we performed Western blot analysis to assess the presence of ApoE on RBCs in 10 patients with light chain amyloidosis." (PMID 41019035, 2025). "Amyloid deposits in the lung and gastrointestinal tract were explored using MALDI-MSI, correlating peptide signatures with ApoE and ApoA1 in AL amyloidosis cases." (PMID 39595194, 2024). "APOE (apolipoprotein E) is a known immune suppressant, which is significantly regulated in many human tumors, but its role in multiple myeloma has not been defined." (PMID 37065484, 2023). "However, we did not detect ApoE, which was often co-deposited in AL amyloidosis, on the surface of RBCs in any patients with AL amyloidosis, suggesting that light chains did not bind to RBCs in the form of amyloid substances." (PMID 41019035, 2025).
non-small cell lung carcinoma (5 papers, 2019 to 2025). A group of at least three distinct histological types of lung cancer, including non-small cell squamous cell carcinoma, adenocarcinoma, and large cell carcinoma. "An elevated level of APOE in the blood of non-small cell lung carcinoma (NSCLC) patients was associated with tumour metastases and poor prognosis." (PMID 36855072, 2023). "Another study has found that IL3 (one of the cytokines), acting in combination with ApoE, promotes the migration and angiogenesis of non-small-cell lung cancer (NSCLC) cells, thus causing metastasis." (PMID 35892323, 2022).
normal tension glaucoma (5 papers, 2009 to 2024). "Since early reports of the APOE ε4 allele’s association with increased risk of normal tension glaucoma in the Tasmanian population, several investigators have examined this link in adult-onset POAG." (PMID 38275738, 2024). "The APOE ε4 allele has also been associated with faster rates of GCIPL (ganglion cell inner plexiform layer) thinning in eyes of normal-tension glaucoma, further solidifying its potential influence across neurodegenerative diseases." (PMID 37834863, 2023). "We observed expression of seven genes which were previously genetically associated with POAG (included normal tension glaucoma (NTG)), namely APOE, CAV1, EDNRA, MYOC, OPTC and TMCO1." (PMID 23028713, 2012).
pneumonia (5 papers, 2021 to 2024). An acute, acute and chronic, or chronic inflammation focally or diffusely affecting the lung parenchyma, caused by an infection in one or both of the lungs (by bacteria, viruses, fungi, or mycoplasma.). "To test this hypothesis, we investigated changes in plaque characteristics and inflammatory features in ApoE−/− mouse aorta and heart following pneumonia." (PMID 35778475, 2022). "The study utilised ratiometric semiconducting polymer nanoparticle (RSPN) photoacoustic imaging to compare lipopolysaccharide caused pneumonia in ApoE−/− mice to non-infected ApoE−/− mice." (PMID 35778475, 2022).
prediabetes (5 papers, 2019 to 2025). "Here, we showed that the plasma levels of apoE are associated with the occurrence of T2D in individuals with prediabetes, independently of traditional risk factors." (PMID 35130909, 2022). "The plasma apoE levels are positively associated with the risk of T2D in prediabetes subjects, independently of traditional risk factors." (PMID 35130909, 2022).
psychological distress (5 papers, 2020 to 2024). "Last but not least, an important concern regarding FH studies, compared to single genetic variants such as APOE ε4, is the possible contribution of the psychological distress caused by the knowledge of being at increased risk of SCD." (PMID 38534745, 2024).
REM sleep behavior disorder (5 papers, 2021 to 2025). A disorder characterized by episodes of vigorous and often violent motor activity during rem sleep (sleep, rem). "Descriptive and comparative statistics of demographic data and frequency of APOE ɛ4 genotype in PD individuals with (right) and without (left) probable REM-sleep behavior disorder (pRBD)." (PMID 36245388, 2022).
retinal degeneration (5 papers, 2009 to 2022). Degeneration of the retina. "APOE is a cholesterol transporter associated with retinal degeneration and hence its accumulation in the subretinal microglia has been reported to exacerbate RD53,54." (PMID 36088481, 2022). "Based on functional and structural analyses, the apoE−/− mouse constitutes a valuable tool in elucidating the underlying mechanism of retinal degeneration." (PMID 23738034, 2013). "Based on biochemical and structural analyses, the apoE−/− mouse is a valuable tool in elucidating the underlying mechanism of retinal degeneration." (PMID 23738034, 2013). "Interestingly, ApoE is a ubiquitous component of drusen, and clinical manifestations of retinal degeneration are exhibited in Apolipoprotein E-deficient mice that carry an ApoE gene that has been inactivated by gene targeting." (PMID 20339564, 2009). "In this study we examined the utility of apoE−/− mice as a model for AMD-like retinal degeneration and the effects of antioxidant treatments on the phenotypical and biochemical changes observed in this model." (PMID 23738034, 2013). "In addition, we had noted the higher number of cells expressing APOE, which plays important role in lipid metabolism and it has been reported in subretinal microglia in other retinal degeneration models." (PMID 36088481, 2022).
Tremor (5 papers, 2011 to 2025). An unintentional, oscillating to-and-fro muscle movement about a joint axis. "The proportion of ApoE ε4 carriers was the same in both groups (13/55, 23.6% tremor versus 57/238, 23.9% controls)." (PMID 26317006, 2014). "The main goal of this work was to describe two MJD patients displaying the parkinsonian triad (tremor, bradykinesia and rigidity), namely on what concerns genetic variation in Parkinson's disease (PD) associated loci (PARK2, LRRK2, PINK1, DJ-1, SNCA, MAPT, APOE, and mtDNA tRNAGln T4336C)." (PMID 22023810, 2011).
vasculitis (5 papers, 2022 to 2024). "In this study, we generated a KD-like vasculitis model using the atherosclerotic animal model, apolipoprotein-E-deficient (ApoE−) mice, and examined how CAWS vasculitis and statins affect vascular senescence and endothelial cell function." (PMID 36555746, 2022). "Candida albicans water-soluble fraction (CAWS) was injected intraperitoneally into 5-week-old male apolipoprotein-E-deficient (Apo E-/-) mice to create KD-like vasculitis." (PMID 35892695, 2022). "Candida albicans water-soluble fraction (CAWS) was administered intraperitoneally to 5-week-old male apolipoprotein E-deficient (ApoE−) mice to induce KD-like vasculitis." (PMID 36555746, 2022). "Our group reported, for the first time, that CAWS vasculitis in mice with apolipoprotein‐E‐deficiency (Apo E−/−) causes chronic macrophage cell infiltration of the aortic root and aortic tissue and that statins may exert an anti‐inflammatory effect by suppressing inflammatory cell infiltration." (PMID 39424429, 2024). "Another study shows that TMAO can partially activate the inflammatory corpuscles of NLRP3 by inhibiting the SIRT3-SOD2-mtROS signaling pathway of apolipoprotein E (ApoE)−/− mice, thus promoting vasculitis." (PMID 39834376, 2024).
age-related hearing loss (4 papers, 2021 to 2025). "Emerging evidence has also linked the ApoE-ε4 allele to age-related hearing loss (ARHL), a prevalent condition characterised by the progressive deterioration of auditory function associated with aging." (PMID 40258814, 2025). "A study published in Scientific Reports in 2024 showed that the ApoE ε4 allele may contribute to the development of Age-Related Hearing Loss (ARHL) by affecting the function and structure of cochlear Spiral Ganglion (SGN) cells." (PMID 40638992, 2025). "Recent studies have implicated ApoE-ε4 in age-related hearing loss (ARHL), suggesting a potential role of APOE4 isoform in peripheral nervous system degeneration." (PMID 40258814, 2025).
Anosmia (4 papers, 2012 to 2023). An inability to perceive odors. "Age, male sex, lower education, Black race, APOE ε4 allele, and vitamin B12 levels were associated with incident anosmia over 5 years." (PMID 37630831, 2023). "In this sample of community-dwelling adults, we found that older age, male sex, lower education, Black race, and APOE ε4 allele were cross-sectionally associated with poor olfactory status, including anosmia." (PMID 37630831, 2023). "On the other hand, older age, male sex, lower education, Black race, and APOE ε4 allele were associated with higher incident anosmia risk over 5 years." (PMID 37630831, 2023). "As with race, we observed that the APOE ε4 carrier status was associated with poor olfaction at visit 5 and elevated anosmia risk at visit 6, but not with longitudinal olfactory decline." (PMID 37630831, 2023).
aortic valve calcification (4 papers, 2021 to 2024). "Subsequently, ApoE−/− mice were fed a high‐fat western diet for an extended period to establish an aortic valve calcification model." (PMID 38502885, 2024). "Prolonged consumption of a western diet by ApoE−/− mice leads to aortic valve calcification." (PMID 38502885, 2024). "ApoE-⁄- animals with aortic valve calcification treated with 100 mg/kg of doxycycline had no lipid-lowering activity and did not affect the gelatinolytic activity of MMPs." (PMID 35269673, 2022).
aortic valve disease (4 papers, 2009 to 2022). "To confirm these results, we established a calcified aortic valve disease mouse model using APOE−/− mice by feeding them a WD for 4 months." (PMID 36405745, 2022).
aortic valve stenosis (4 papers, 2011 to 2023). Aortic valve stenosis (AVS) is a condition characterized by narrowing of the heart's aortic valve opening. "This study demonstrated that targeted aortic valve irradiation in ApoE−/− mice resulted in the development of an aortic valve remodeling that mimics the human radiation-induced aortic valve stenosis, with a higher effect than in WT animals." (PMID 37762794, 2023).
Ataxia (4 papers, 2006 to 2022). Ataxia refers to impaired coordination of voluntary muscle movement. "All these cells and structures are implicated in the occurrence of ataxia possibly modulated by APOE." (PMID 36508411, 2022). "The evaluation of the correlation between clinical/neurophysiological data and APOE ɛ4 carrying status revealed a correlation of the carriage of APOE ɛ4 allele and ataxia duration in MSA-P patients." (PMID 36508411, 2022). "We also reported in our study the significant correlation of ataxia duration with the carriage of APOE ɛ4 isoform." (PMID 36508411, 2022). "Apolipoprotein E, Amyloid beta precursor-like protein, Amyloid βeta precursor protein, Spinocerebellar ataxia gene, Synapsin 1, Endothelin receptor, S100 (callizzarin), Nieman-Pick type C2." (PMID 16696860, 2006).
autism (4 papers, 2019 to 2025). Persistent deficits in social interaction and communication and interaction as well as a markedly restricted repertoire of activity and interest as well as repetitive patterns of behavior. "Four of these studies used different genetic models of autism such as BTBR mice and KO reeler mice and other genes that could potentially modulate social behavior such as the different polymorphism of the human Apolipoprotein E (APOE)." (PMID 34068255, 2021).
breast tumor (4 papers, 2019 to 2024). "In our study, we revealed that Cd68+ApoE+ cells were found in the TMEs of lung metastatic breast tumors were correlated with C1qa/b/c, Cd74, and ApoE expression." (PMID 39695088, 2024). "To test this, we examined whether expression of NR1H3/LXRA or NR1H2/LXRB correlated with expression of canonical LXR target genes (ABCA1 and APOE) in 81 ER-negative or 234 ER-positive primary breast tumours (obtained from TCGA dataset)." (PMID 31683867, 2019). "Vehicle control, GW3965, 26-OHC (the most abundant scOHC in breast tumour tissue) or 24,25-EC (the scOHC that elicited the greatest fold induction in reporter cells) were added to MDA-MB-468 or MCF7 cells for 4 or 16 h and changes to ABCA1 and APOE expression determined." (PMID 31683867, 2019).
cerebral edema (4 papers, 2017 to 2024). "The greater reduction in microcirculation perfusion was associated with more severe brain edema and lower Rota rod latency in the ApoE-deficient mice than in the WT mice." (PMID 34566870, 2021). "For example, APOE-ε4 genotype status was associated with increased cerebral edema and brain inflammation, which might result in slower brain recovery that in turn negatively influences cognitive performance early after MTBI." (PMID 35250800, 2022).
cerebral malaria (4 papers, 2008 to 2025). A sequestration of Plasmodium falciparum in the brain, which can cause coma and/or seizures. "ApoE is the dominant apolipoprotein in the brain and has been implicated in several neurological disorders; therefore, we were interested in the potential role of ApoE in cerebral malaria." (PMID 27647324, 2016). "Thus, we were interested in determining the specific impact of ApoE deficiency on cerebral malaria." (PMID 27647324, 2016). "100% of the WT mice displayed the characteristic symptoms of cerebral malaria and succumbed to the infection, whereas the ApoE−/− mice were significantly protected, with an ECM incidence of only 25%." (PMID 27647324, 2016). "Overall, we have clearly demonstrated that ApoE is essential to the development of cerebral malaria." (PMID 27647324, 2016). "Both routes of OCTA administration provided substantial protection from ECM, suggesting that heparin-mediated ApoE antagonism is promising as a treatment for cerebral malaria." (PMID 27647324, 2016). "Importantly, we demonstrated that treatment of mice with the ApoE antagonist heparin octasaccharide significantly decreased the incidence of cerebral malaria." (PMID 27647324, 2016). "Overall, our study indicates that the reduction of ApoE could be utilized in the development of therapeutic treatments aimed at mitigating the neuropathology of cerebral malaria." (PMID 27647324, 2016). "We observed that the mice fed a high-fat diet were as susceptible to cerebral malaria as the mice fed the standard chow, suggesting that the elevated total cholesterol in the ApoE−/− mice does not contribute to the protective phenotype." (PMID 27647324, 2016). "The surviving ApoE−/− mice did not display any of the hallmark clinical symptoms of cerebral malaria, such as limb paralysis, convulsions and coma." (PMID 27647324, 2016). "Therefore, we were interested in elucidating whether ApoE played a role in the development of cerebral malaria pathology." (PMID 27647324, 2016). "Herein we report that ApoE−/− mice are significantly protected against cerebral malaria, and that pharmacological inhibition of ApoE using heparin octasaccharide (OCTA) could represent a new avenue in the development of adjunctive therapies for cerebral malaria." (PMID 27647324, 2016). "Therefore, we investigated whether this change in the lipid profile contributed to the enhanced protection from cerebral malaria observed in the ApoE−/− mice." (PMID 27647324, 2016). "Most importantly, we have demonstrated that the treatment of mice with the ApoE antagonist OCTA significantly decreases the incidence of ECM and that OCTA has the potential to be used in the development of novel cerebral malaria adjunctive therapies." (PMID 27647324, 2016). "The incidence of ECM was not significantly decreased in the ApoA1−/− mice compared to the WT mice, suggesting that the decreased level of HDL cholesterol is not responsible for the protection against cerebral malaria observed in the ApoE−/− mice." (PMID 27647324, 2016). "Furthermore, the WT mice displayed the characteristic features of cerebral malaria, but the ApoE−/− mice that survived the cerebral phase did not display these symptoms." (PMID 27647324, 2016). "We report the first demonstration that the absence of ApoE protects mice from cerebral malaria." (PMID 27647324, 2016).
chronic hepatitis (4 papers, 2018 to 2025). An active inflammatory process affecting the liver for more than six months. "Our observation of the C1q-ApoE complex in acute and chronic hepatitis opens the way for another therapeutic strategy involving ApoE itself." (PMID 36304458, 2022).
Creutzfeldt-Jakob Disease (4 papers, 2011 to 2024). "This study aimed to assess the prevalence of APOE genotypes (ε2, ε3, ε4) and PRNP mutations (E200K, M129V) in the general population of Pakistan because of their association with RPDs, including Rapidly Progressive Alzheimer’s Disease (rpAD) and Creutzfeldt-Jakob Disease (CJD)." (PMID 39654135, 2024).
cutaneous melanoma (4 papers, 2013 to 2022). A primary melanoma arising from atypical melanocytes in the skin. "Furthermore, significant expression differences of APOE were observed between tumor and normal tissues of GBM, Brain lower grade glioma (LGG), Lymphoid neoplasm diffuse large B-cell lymphoma (DLBC), TGCT, Skin cutaneous melanoma (SKCM), and Thymoma (THYM) (p < 0.001)." (PMID 37304007, 2022). "Also, APOE did not correlate with survival at a 30% bifurcate gene analysis, whereas the expression of PD-L1 and PD1 both positively correlated with survival of cutaneous melanoma." (PMID 36341364, 2022).
demyelinating disease (4 papers, 2013 to 2025). A broad group of disorders that affect the myelin sheaths that cover the neurons. "Considering the roles of apoE in facilitating lipid uptake by OLs and the reduction of inflammation, apoE-mimetic strategy may represent a novel therapeutic approach for the treatment of demyelinating disorders such as MS and SCI." (PMID 25642353, 2013). "Thus, we hypothesize that apoE may represent an ideal target for development of novel therapeutics for MS and other demyelination diseases based on its roles in reducing inflammation and promoting myelination and regeneration." (PMID 25642353, 2013). "New and innovative avenues for the investigation and treatment of demyelinating disorders are required that involve autophagy, apoptosis, FoxOs, mTOR, AMPK, SIRT1, and related systems with the APOE-ε4 gene and SARS-CoV-2." (PMID 37508898, 2023).